UBR7 (ubiquitin protein ligase E3 component n-recognin 7)
Description:
E3 ubiquitin-protein ligase which is a component of the N-end rule pathway. Recognizes and binds to proteins bearing specific N-terminal residues that are destabilizing according to the N-end rule, leading to their ubiquitination and subsequent degradation.
Synonyms: C14orf130; LICAS
Tractability: PROTAC: UniProt records ubiquitination sites on it; ubiquitination databases record sites on it; its protein half-life has been measured.
Target class: Enzyme; Transferase
Gene: Protein-coding gene on chromosome 14 (93,207,241 to 93,229,215, forward strand). Ensembl gene ENSG00000012963.
Subcellular location (Human Protein Atlas): Nucleoplasm
Gene Ontology:
Molecular function: ubiquitin protein ligase activity; zinc ion binding
Biological process: proteasome-mediated ubiquitin-dependent protein catabolic process; protein ubiquitination
Genetic constraint (gnomAD): Loss-of-function variants: 18 observed, 43.86 expected, observed/expected ratio (o/e) 0.41, 90% interval 0.28 to 0.61. The upper end of that interval is the gene's LOEUF score, 0.61, which puts it in group 2 of 6, group 1 being the genes least tolerant of losing a copy. Missense variants: 377 observed, 456.27 expected, observed/expected ratio (o/e) 0.83, 90% interval 0.76 to 0.9. Synonymous variants: 158 observed, 161.91 expected, observed/expected ratio (o/e) 0.98, 90% interval 0.86 to 1.11.
Homologues: Orthologues: chimpanzee UBR7 (100% identical), macaque UBR7 (98% identical), dog UBR7 (92% identical), guinea pig UBR7 (90% identical), rabbit UBR7 (89% identical), rat Ubr7 (88% identical), mouse Ubr7 (87% identical), pig UBR7 (82% identical), tropical clawed frog ubr7 (63% identical), zebrafish ubr7 (55% identical), Drosophila melanogaster CG15141 (36% identical), Caenorhabditis elegans T22C1.1 (26% identical).
Diseases named in the same sentence as UBR7 in open-access papers:
UBR7 is named in the same sentence as 14 diseases in open-access papers, as found by Europe PMC text mining. Sharing a sentence is not in itself a finding about the gene and the disease. The quoted sentences say what the papers report.
breast carcinoma (5 papers, 2019 to 2022). "Importantly, we found UBR7 loss to be highly correlated with triple-negative and basal-like breast cancer." (PMID 30923315, 2019). "UBR7 loss may be a key determining feature of this aggressive subtype of breast cancer." (PMID 30923315, 2019). "Similar observations have been found in breast cancer that UBR7 acts as an H2BK120ub ligase and a tumor suppressor." (PMID 36419136, 2022). "Collectively, our results demonstrated that UBR7 is a H2B E3 ubiquitin ligase that suppresses triple-negative subtype of breast cancer by activating CDH4/R-cadherin expression and inhibiting the canonical Wnt/β-catenin signaling pathway." (PMID 30923315, 2019). "This analysis revealed reduced UBR7 expression in triple-negative and basal-like breast tumors, which was confirmed in an independent cohort of breast cancer tissue microarrays (TMAs) containing 371 breast tumors using a UBR7-specific antibody." (PMID 30923315, 2019). "We observed lower UBR7 levels in human and murine breast cancer cells than in their “normal” counterparts." (PMID 30923315, 2019). "Among other candidates of H3.1‐interactors, the PHD finger protein (AT4G23860) was identified as a homologue of human histone H3‐binding UBR7 E3 ubiquitin ligase, which mediates K120 ubiquitination of histone H2B and acts as breast cancer tumour suppressor." (PMID 31276249, 2019). "Here, the authors show that UBR7 PHD finger is a H2BK120 monoubiquitin ligase that acts a tumour suppressor in breast cancer by suppressing gene expression for EMT, while promoting expression of CDH4 which restrain WNT/β-cat pathway." (PMID 30923315, 2019). "Although we showed that UBR7 prevents metastatic colonization and represses genes that are crucial for breast cancer metastasis by targeting CDH4, other downstream pathways and target genes may also have important roles." (PMID 30923315, 2019). "Furthermore, CDH4 expression exhibited consistent patterns to UBR7 in matched “normal” and “malignant” breast cancer cell lines." (PMID 30923315, 2019). "Furthermore, UBR7 was associated with a better metastasis-free survival rate in the aggressive basal-type breast cancer (mesenchymal subtype tumors without endocrine therapy)." (PMID 30923315, 2019). "Despite the anti-cancer function in solid tumors like breast cancer and HCC, UBR7 was identified as transcriptional target of NOTCH1 and played an oncogenic role in T cell acute lymphoblastic leukemia." (PMID 36419136, 2022). "Consistently, UBR7-WT, but not UBR7-CM, increased H2BK120Ub levels in the MDA-MB-231 and MDA-MB-468 breast cancer cells." (PMID 30923315, 2019). "Similarly, overexpression of UBR7-WT, but not UBR7-CM, in MDA-MB-231 and MDA-MB-468, two basal-like breast cancer cells that express UBR7 at low levels, dramatically reduced 2D proliferation." (PMID 30923315, 2019).
acute lymphoblastic leukemia (2 papers, 2021 to 2024). Leukemia with an acute onset, characterized by the presence of lymphoblasts in the bone marrow and the peripheral blood. "UBR7 stabilizes the phosphoribosyl pyrophosphate synthetase (PRPS) catalytic subunits by mediating the degradation of PRPS-related proteins (negative regulators of PRPS) caused by polyubiquitination and then regulates nucleotide metabolism in acute lymphoblastic leukemia." (PMID 39424627, 2024).
hepatocellular carcinoma (2 papers, 2023 to 2024). A malignant tumor that arises from hepatocytes. "In hepatocellular carcinoma, UBR7 inhibits glycolysis by indirectly suppressing HK2 expression." (PMID 38495480, 2024).
pancreatic cancer (2 papers, 2024). "Finally, an inhibitor that blocks PRMT5 (DS-437) significantly reduced gemcitabine resistance in pancreatic cancer caused by UBR7 depletion." (PMID 39424627, 2024). "Moreover, the same inhibitor also demonstrated that inhibition of PRMT5 significantly reduced gemcitabine resistance in pancreatic cancer caused by UBR7 depletion." (PMID 39703687, 2024). "The mechanism of UBR7 in tumor resistance, especially in gemcitabine-resistant pancreatic cancer, has rarely been reported." (PMID 39424627, 2024). "To further analyze the effect of exhausted UBR7 on immune cells in the microenvironment of pancreatic cancer tissues, we performed a refined subpopulation analysis of T cells." (PMID 39424627, 2024). "Overexpression of UBR7 in pancreatic cancer cells significantly reduced cell viability and proliferation capacity." (PMID 39424627, 2024). "Furthermore, we found that depletion of UBR7 promoted pancreatic cancer progression and an immunosuppressive microenvironment." (PMID 39424627, 2024). "In addition, we found that the expression level of UBR7 in normal pancreatic cells was significantly higher than that in pancreatic cancer cells." (PMID 39424627, 2024). "Furthermore, this study provides a rationale for a clinical regimen that blocks PRMT5-mediated glycolysis in patients with gemcitabine-resistant UBR7-depleted pancreatic cancer." (PMID 39424627, 2024). "In addition, the protein and mRNA levels of UBR7 in the gemcitabine-resistant cell line PANC-1-GEM were significantly lower than those in normal pancreatic cancer cell lines." (PMID 39424627, 2024). "Therefore, we speculated that UBR7 regulated glycolysis in pancreatic cancer by regulating the expression of PRMT5, thereby promoting drug resistance." (PMID 39424627, 2024). "Thus, we hypothesized that UBR7 might play an important role in gemcitabine resistance in pancreatic cancer." (PMID 39424627, 2024). "Depletion of UBR7 increased PRMT5 protein stability, which in turn increased glycolysis in pancreatic cancer cells and Tregs." (PMID 39424627, 2024). "Mechanistically, depleted UBR7 increased the stability of PRMT5, thereby promoting glycolysis in pancreatic cancer cells." (PMID 39424627, 2024). "Taken together, these results indicate that UBR7 regulates the progression and GEM resistance of pancreatic cancer by regulating the expression of PRMT5." (PMID 39424627, 2024). "In this study, we performed functional enrichment analysis of differentially expressed genes in Tregs in KC and KC;UBR7−/− pancreatic cancer tissues and showed that depletion of UBR7 increased glycolysis in Tregs, which was not experimentally verified." (PMID 39424627, 2024). "In conclusion, we found that UBR7 is depleted in gemcitabine-resistant PDAC and further found that depleted UBR7 stabilizes PRMT5 to increase pancreatic cancer cell and Treg cell glycolysis, leading to pancreatic cancer progression and an immunosuppressive microenvironment." (PMID 39424627, 2024). "Mechanistically, UBR7 also monoubiquitinated histone H2B in pancreatic cancer cell lines, but did not function." (PMID 39424627, 2024). "In addition, we examined whether UBR7 transfers ubiquitin to its substrate histone H2BK120 and plays a role in pancreatic cancer cells." (PMID 39424627, 2024). "This indicates that UBR7 plays a role in ubiquitination of H2B in pancreatic cancer cells, but may not rely on ubiquitination of H2B to function." (PMID 39424627, 2024).
T-cell acute lymphoblastic leukemia (2 papers, 2021 to 2022). Acute lymphoblastic leukemia of T-cell origin. "Moreover, a novel nucleotide biosynthesis regulatory role for UBR7 has been identified in NOTCH1-driven T cell acute lymphoblastic leukemia." (PMID 36419136, 2022).
triple-negative breast carcinoma (2 papers, 2019 to 2024). An invasive breast carcinoma which is negative for expression of estrogen receptor (ER), progesterone receptor (PR), and human epidermal growth factor receptor 2 (HER2). "Studies have found that UBR7 monoubiquitinated histone H2B inhibits triple-negative breast cancer tumorigenesis and metastasis." (PMID 39424627, 2024). "Low UBR7 expression was correlated with occurrence of triple-negative breast cancer and metastatic tumors." (PMID 30923315, 2019). "Overall, these results establish the tumor- and metastasis-suppressive functions of UBR7 in triple-negative breast cancer." (PMID 30923315, 2019). "Collectively, our results established UBR7 as a histone H2B monoubiquitin ligase that suppresses tumorigenesis and metastasis of triple-negative breast cancer." (PMID 30923315, 2019). "In the present study, we demonstrated that the UBR7-PHD finger is an H2BK120 monoubiquitin ligase and a tumor suppressor in triple-negative breast cancer cases." (PMID 30923315, 2019).
Autoimmunity (1 paper, 2023). The occurrence of an immune reaction against the organism's own cells or tissues. "So we wondered if insects also have a protein similar to plant UBR7 involved in autoimmunity." (PMID 37187513, 2023). "In addition, UBR7 harbors a PHD finger domain (142–193 AAs) and a conserved zinc finger domain (51–115 AAs), which can specifically recognize histone modifications and some DNA sequences that participate in plant life processes including plant autoimmunity." (PMID 37187513, 2023).
breast tumors (1 paper, 2019). "Whereas UBR7 loss promotes breast tumor metastasis, CDH4 overexpression provides only a partial rescue of such phenotypes." (PMID 30923315, 2019). "Notably, we established that UBR7 can suppress breast tumor formation and metastasis in vivo." (PMID 30923315, 2019).
dysplasia (1 paper, 2024). A usually neoplastic transformation of the cell, associated with altered architectural tissue patterns. "Compared with the KC control, the age-matched KC;Ubr7–/– pancreas showed faster development of pancreatic dysplasia, increased pancreatic weight, increased fibrosis around the pancreas and shortened lifespan." (PMID 39424627, 2024).
metastatic tumors (1 paper, 2019). "Consistent with a metastasis-suppressive role for UBR7 and its lower levels in metastatic tumors, UBR7-WT overexpressing MDA-MB-231 cells, but not UBR7-CM-overexpressing MDA-MB-231 cells, were unable to seed to the lung upon intravenous injection, whereas control cells formed overt lung metastases." (PMID 30923315, 2019).
tumor (7 papers, 2019 to 2025). "In vivo evidence further highlighted the importance of glycolysis in UBR7 deficiency-induced tumor growth as glycolysis inhibitors completely abolished the promoting effect elicited by silencing UBR7." (PMID 36419136, 2022). "Pharmaceutical and genetic inhibition of glycolytic enzymes attenuate the promoting effect of UBR7 deficiency on tumor growth." (PMID 36419136, 2022). "Pharmaceutical and genetic inhibition of glycolytic enzymes diminishes the stimulatory effect of UBR7 deficiency on tumor growth." (PMID 36419136, 2022). "Ubiquitin protein ligase E3 component N-recognin 7 (UBR7) is downregulated in HCC, and its loss promotes HCC tumor proliferation and formation." (PMID 39980550, 2025). "Further functional cluster analysis of the differentially expressed genes in Treg cells in KC and KC; Ubr7–/– tumor tissues revealed that the glycolysis-related genes of Treg cells in KC;Ubr7–/– tumor tissues were significantly increased." (PMID 39424627, 2024). "Among them, we found that compared with KC tumor tissue, Treg cells in KC;Ubr7-/- tumor tissue were significantly increased." (PMID 39424627, 2024). "We detected the expression level of UBR7 in the PDX tumor tissues of the sensitive group and the resistant group." (PMID 39424627, 2024). "We used scRNA-seq to analyze the unfractionated CD45+ cell mixtures of KC and KC;Ubr7–/– tumor tissues." (PMID 39424627, 2024). "The results showed that the protein and mRNA levels of UBR7 in the tumor tissues of the resistant group were significantly lower than those in the PDX tumor tissues of the sensitive group." (PMID 39424627, 2024). "Consistently, UBR7 loss was observed in both GISTIC database and primary liver tumor samples, suggesting a putative tumor suppressive function." (PMID 36419136, 2022). "In contrast to normal adjacent tissues, UBR7 protein levels were notably lower in primary tumor tissues, implying the potential tumor-suppressive activity of UBR7 in HCC." (PMID 36419136, 2022). "Clinicopathological analysis was further constructed to demonstrate the clinical significance of UBR7, especially in terms of tumor diameter and differentiation." (PMID 36419136, 2022). "Overall, the results derived from human datasets and clinical samples strongly supported the possibility that UBR7 act as a tumor suppressor in HCC by regulating Keap1/Nrf2/Bach1/HK2 axis." (PMID 36419136, 2022). "A series of loss-of-function and gain-of-function experiments established the role of UBR7 as a tumor and metastasis suppressor gene." (PMID 30923315, 2019). "Therefore, we further explored the potential effect of UBR7 depletion on the PDAC tumor microenvironment." (PMID 39424627, 2024). "In addition, we also found that CD4+ and CD8+ T cells secreted PD-1, granzyme B, CD107a and TNF-α levels in tumor tissues of KC;Ubr7–/– mice were significantly reduced." (PMID 39424627, 2024). "We found that overexpression of UBR7 could effectively reduce the size of tumors, while the tumor after simultaneous overexpression of PRMT5 weight was larger." (PMID 39424627, 2024). "Notably, Hemin treatment almost fully abolished the effects of UBR7 depletion on colony formation, as well as tumor weight, lymph node metastasis, and lymph node size." (PMID 36419136, 2022). "Furthermore, coincident observations were achieved by xenograft model, showing that the promoting effects of UBR7 decline on tumor growth and metastasis was impaired by silencing HK2." (PMID 36419136, 2022). "To further characterize the connection between UBR7-mediated glycolysis and tumor growth in HCC, we next evaluated whether drugs, which target enzymes involved in glycolysis, could affect UBR7-deficiency induced tumorigenesis." (PMID 36419136, 2022). "Conversely, ectopic expression of UBR7 restored these cellular phenotypes and reduced tumor growth." (PMID 30923315, 2019).
tumor (continued). "Mechanistically, UBR7 inhibits HCC glycolysis through the Keap1/Nrf2/Bach1/HK2 signaling axis, and exerting a tumor suppressive effect." (PMID 39980550, 2025). "Taken together, these data suggest that UBR7 plays a potent role in regulation of lactate acid levels in HCC, which might contribute to tumor suppression." (PMID 36419136, 2022). "Besides, the protein levels of UBR7 was significantly lower in HCC tissue, which differed with the stage of tumor development." (PMID 36419136, 2022). "Importantly, such inhibitions caused by UBR7 overexpression were not obvious in HCC cells transfected with UBR7-CM, which again highlighted the importance of UBR7’s catalytic activity on its tumor-suppressive function." (PMID 36419136, 2022). "The evidence from this study showing silencing of UBR7 mitigates tumor formation from both GSI sensitive and resistant T-ALL cell lines, opens a new therapeutic window and suggest future efforts should be directed towards developing clinical inhibitors against UBR7." (PMID 34188174, 2021). "Overexpression of UBR7-WT and not UBR7-CM abrogated mammary fat pad tumor formation in vivo." (PMID 30923315, 2019).
cancer (4 papers, 2019 to 2024). A tumor composed of atypical neoplastic, often pleomorphic cells that invade other tissues. "Also, metastatic intraductal carcinomas harbored considerably lower levels of UBR7 than did primary tumors." (PMID 30923315, 2019). "Thus, further investigation is needed to fully elucidate the conflicting role of UBR7 in cancer." (PMID 36419136, 2022).
UBR7 also shares sentences with these, for which no sentence is quoted: infection (1 paper); ovarian carcinoma (1).